DHCR24 (24-dehydrocholesterol reductase)
Diseases named in the same sentence as DHCR24 in open-access papers (continued):
Sharing a sentence is not in itself a finding about the gene and the disease.
infection (8 papers, 2012 to 2023). The state of being infected such as from the introduction of a foreign agent such as serum, vaccine, antigenic substance or organism. "We observed that genes involved in cholesterol uptake (Lrp2) (denoted in grey across the figures) and biosynthesis (Aacs, Hmgcs1, Mvd, Dhcr24) were significantly upregulated during infection; while those implicated in efflux (Abca1, Abcg1) showed a marked downregulation." (PMID 37871034, 2023). "IFNγ-induced decrease in Fasn and Fads2 expression correlated with reduced Abca1 and Dhcr24 transcript levels after 6 hr of infection, suggesting that IFNγ prevents Mtb-induced stimulation of FA biosynthesis through downregulation of LXR and SREBP1 activity." (PMID 34951591, 2021). "Infection with Ad-DHCR24-myc significantly increased the attached cell numbers exposed to cholesterol and H2O2, suggesting that upregulation of DHCR24 protected MIN6 cells against apoptosis caused by oxidative stress." (PMID 32724824, 2020). "HCV gene expression or infection persistently induces over-expression of DHCR24 in its turn induces apoptotic resistance to oxidative stress." (PMID 23203124, 2012). "As DHCR24 catalyzes desmosterol to cholesterol during the last step of cholesterol biosynthesis, we next investigated whether the intracellular cholesterol levels were affected by infection with Ad-LacZ or Ad-DHCR24-myc." (PMID 32724824, 2020). "DHCR24 and TPPP3 genes showed limited to no variance in the infection severity." (PMID 33602138, 2021).
neurodegenerative disease (3 papers, 2017 to 2022). A disorder of the central nervous system characterized by gradual and progressive loss of neural tissue and neurologic function. "Thus, accumulating evidences strongly reveal that cholesterol loss by DHCR24 downregulation could lead to Aβ overproduction, tau hyperphosphorylation, and other pathological impairments which are associated with neurodegenerative diseases such as AD." (PMID 35296367, 2022). "Thus, evidences suggest that the downregulation of DHCR24 induced by the depletion of neurosteroids and neurotrophic factors in the brain might play a pivotal pathological role in neurodegenerative diseases." (PMID 35296367, 2022). "However, the role of DHCR24 in neuroinflammation, which is a key feature in several neurodegenerative diseases, has not been assessed previously." (PMID 29115990, 2017).
adenocarcinoma (2 papers, 2022 to 2023). A common cancer characterized by the presence of malignant glandular cells. "Using IHC, the protein expressions of CRABP2, DHCR24, and AK4 were examined using 44 adenocarcinomas including AIS (n = 7), MIA (n = 21), and SIA (n = 16)." (PMID 37004157, 2023). "We found high expression of DHCR24 in 281 (77.2%) CRC tissues, especially adenocarcinoma tissues (OR = 2.38, P = 0.036)." (PMID 35501301, 2022).
cardiovascular diseases (1 paper, 2025). "In addition, targeting DHCR24 (24-dehydrocholesterol reductase) to increase endogenous desmosterol levels has been recognized as a promising strategy to activate the LXR transcriptional program, enhance ABCA1-mediated cholesterol efflux, and counteract atherosclerotic cardiovascular diseases." (PMID 41303341, 2025).
neurological disorder (1 paper, 2024). "Notably, 7-days post-TBI saw the dysregulation of pathways such as DHCR24 and LXR/RXR signaling, along with the early onset of neurological disorder and prostaglandin metabolism, indicating secondary and potentially chronic developments." (PMID 38735925, 2024).
DHCR24 also shares sentences with these, for which no sentence is quoted: dyslipidemia (3 papers); coronary artery disease (2); genetic disease (2); metabolic disease (2); adenoma (1); aging (1); autism (1); Bartter syndrome type 4a (1); cerebral small vessel disease (1); chronic hepatitis (1); chronic hepatitis C (1); Cirrhosis (1); epilepsy (1); Epileptic encephalopathy (1); Failure to thrive (1); familial Alzheimer disease (1); Granuloma (1); gynecological cancers (1); heart failure (1); Hepatic fibrosis (1); Huntington disease (1); Hyperinsulinemia (1); hypertriglyceridemia (1); hypothyroidism (1); Insulin resistance (1); lathosterolosis (1); limb ischemia (1); liver cirrhosis (1); lymph node metastasis (1); male infertile (1).
A further 15 diseases each share a sentence with DHCR24 in 1 paper.